RNU7-136P (RNA, U7 small nuclear 136 pseudogene)
Gene: Small nuclear RNA gene on chromosome 3 (160,472,348 to 160,472,416, reverse strand). Ensembl gene ENSG00000238427.
Homologues: Orthologues: chimpanzee U7 (100% identical), macaque U7 (100% identical). Paralogues in human: RNU7-48P (75% identical), RNU7-88P (75% identical), RNU7-120P (74% identical), RNU7-20P (74% identical), RNU7-7P (74% identical), RNU7-84P (74% identical), RNU7-124P (72% identical), RNU7-197P (72% identical), RNU7-19P (72% identical), RNU7-37P (72% identical), RNU7-40P (72% identical), RNU7-43P (72% identical), and 142 more.